PROCR (protein C receptor)
Diseases named in the same sentence as PROCR in open-access papers (continued):
Sharing a sentence is not in itself a finding about the gene and the disease.
Turner syndrome (1 paper, 2017). Turner syndrome is a chromosomal disorder associated with the complete or partial absence of an X chromosome. "Eight TFs and four ERFs are among the differentially expressed genes, as well as eight genes associated with Turner syndrome (PROCR, NR3C1, INSR, APOB, BMP15, F8, IL6, and WAS) and two genes that are haploinsufficient in humans (RAD50 and SLC33A1)." (PMID 28818098, 2017).
cancer (41 papers, 2005 to 2026). A tumor composed of atypical neoplastic, often pleomorphic cells that invade other tissues. "Immunohistochemistry showed that key markers identifying this putative Tr-CAF subset—CXCL14, ADAMDEC1, EDNRB, and PROCR—were predominantly localized to fibroblasts within normal colonic mucosa and less frequently in cancer-associated fibroblasts (CAFs)." (PMID 40759242, 2025). "Significantly, molecular targeting of SMAD5 expression was linked to inhibition of a CD44+/CD24-/PROCR+ cancer stem cell-like phenotype and low ALDH1 activity." (PMID 29207686, 2017). "The protein C receptor (PROCR) belongs to the blood coagulation pathway and has been linked both to aging-associated diseases (like cardiovascular diseases) and cancer." (PMID 23889843, 2013). "PROCR, implicated in various biological processes such as inflammation and vascular biology, suggests potential implications for the tumour microenvironment and cancer progression." (PMID 38490958, 2024). "TF-FVIIa-Xa ternary complex signaling in endothelial, smooth muscle and cancer cells also requires the endothelial cell protein C receptor (EPCR)." (PMID 33893900, 2021). "Endothelial protein C receptor (PROCR) belongs to the protein C pathway that controls blood coagulation as well as cancer progression." (PMID 27894102, 2016). "Taking these results together, the PROCR+/ESA+ subpopulation of MDA-MB-231 cells was indeed comprised of cancer stem cells." (PMID 20027313, 2009). "While in NPC, the protein C receptor sustains cancer stemness through lipid synthesis activation." (PMID 41522354, 2026). "In addition, TECs can promote cancer cell progression and metastasis by expressing endothelial protein C receptor (EPCR) and NOTCH1." (PMID 37666813, 2023). "The EPCR gene (PROCR), though rarely mutated in any cancer type, was frequently amplified." (PMID 28770100, 2017). "However, for activated protein C (APC) protease to cleave the N-terminus of PAR-1 in cancer cells, the endothelial protein C receptor (EPCR) is required as a cofactor." (PMID 26573921, 2015). "The objective of this study was to assess whether soluble plasma endothelial protein C receptor (sEPCR), which is a regulator of circulating aPC, is involved in innate immune response in cancer patients." (PMID 23877403, 2013). "Therefore, assuming that younger patients have a higher PROCR expression, the AA genotype might impose an additive effect by increasing EPCR activity, consequently favouring cancer pathways." (PMID 37308506, 2023). "Interestingly, we found several of these genes (ATP8B3, FOXR2, FRG2, HIST1H4A) to act as cancer stemness regulators, able to regulate cancer stem cell self-renewal activity and expression of the endothelial protein C receptor (EPCR), a specific stemness marker for TNBC." (PMID 37932309, 2023). "Endothelial protein C receptor (EPCR) and PARs play important roles in both cancer growth and dissemination, and, moreover, the interactions between the two receptors are essential for tumor progression." (PMID 35328684, 2022). "Endothelial protein C receptor (EPCR) and protease activated receptor 1 (PAR-1) by themselves play important role in cancer growth and dissemination." (PMID 30626007, 2019). "It is now clear that the protease activated cell surface transmembrane receptors, endothelial protein C receptor (EPCR) and protease activated receptor 1 (PAR-1), apart from their roles in hemostasis and inflammation, influence cancer biology." (PMID 30626007, 2019). "The recent review article by Marek Z. Wojtukiewicz and co-workers provides a comprehensive overview of the impact of endothelial protein C receptor (EPCR; CD201) and protease-activated receptor-1 (PAR-1), traditionally related to the blood coagulation cascade, on cancer growth and metastasis." (PMID 30884838, 2019).
tumor (39 papers, 2005 to 2025). "Recent studies have found that the protein C receptor (PROCR), which is associated with poor prognosis in patients with NPC, has the potential to maintain the stemness of tumor cells by regulating lipid metabolism and mitochondrial fission." (PMID 39015496, 2024). "H&E, PROCR, and EpCAM staining of resected tumors revealed PROCR+ spindle-like tumor cells with pockets of PROCR+/EpCAM+ tumor cells." (PMID 37709737, 2023). "PROCR can promote tumor angiogenesis in vitro by activating ERK1/2 and AKT in GC cells, dependent on the activation of PAR1." (PMID 33794777, 2021). "In spite of the growing importance of endothelial protein C receptor/active protein C (EPCR/aPC) in tumor biology, their impact on immunological homeostasis remains largely unexplored." (PMID 23877403, 2013). "There was an association between metastasis status and a high prevalence of certain markers including CD44+/CD24−/low, ESA+, CD133+, CXCR4+ and PROCR+ in primary tumor cells." (PMID 20027313, 2009). "Additionally, PROCR is reported to be vital for cell division, apoptosis, proliferation, and tumor recurrence." (PMID 40332167, 2025). "Moreover, blockage of PKA or NFκB also inhibited subcutaneous tumor growth and femur xenograft metastasis in vivo, further confirming the orchestrated signaling cascade triggered by PROCR." (PMID 35169126, 2022). "In addition, we also found that the tumor promoting effect of PROCR was dependent on exogeneous APC treatment to a great extent." (PMID 35169126, 2022). "Since PROCR knockdown could significantly ameliorate tumor growth in transplantation, the therapeutic potential of ADAM17 in TNBC is worth investigating." (PMID 34281556, 2021). "Consistent with the soft agar colony formation assays, PROCR+/ESA+ cells were highly tumorigenic since tumor formation could be observed from a starting population of as little as 100 PROCR+/ESA+ cells within 50 days." (PMID 20027313, 2009). "We then asked whether PROCR acts as a functional gene in tumor cells." (PMID 35169126, 2022). "The endothelial protein C receptor (PROCR) is expressed by a variety of tumor cell types, and protein C appears to stimulate tumor cell proliferation, migration, and metastasis; thus, increased expression of PROCR in melanocytes may stimulate them to proliferate and migrate." (PMID 22745913, 2012). "Other regulators of tumor biology, including PTPRS, CSPG4, SPRED1, CD59, and PROCR, were all downregulated upon CBX3 knockdown." (PMID 39545414, 2024). "Functional analysis reveals that protein C receptor (PROCR) not only serves as a stem cell marker in NPC, but also maintains tumor cells’ stemness potential through regulating lipid metabolism and mitochondrial fission." (PMID 35169126, 2022). "Vδ5+ γδ T cells co-expressing Vγ4 recognize endothelial protein C receptor (EPCR) on cytomegalovirus (CMV)-infected epithelial cells and epithelial tumor cells via TCR." (PMID 32413966, 2020). "The results showed that GFP+ cells accounted for the majority of tumor xenografts in the lungs in the presence of PROCR overexpression, but not in the PROCR knockout cells." (PMID 35169126, 2022). "In this regard, we think that the activated lipid metabolism in tumor cells may not be PROCR specific, although their excessive activation is clearly induced by PROCR overexpression." (PMID 35169126, 2022).
infection (18 papers, 2012 to 2024). The state of being infected such as from the introduction of a foreign agent such as serum, vaccine, antigenic substance or organism. "The γδTCR can also recognize ligands induced by infection or stress, like annexin A2 and endothelial protein C receptor (EPCR)." (PMID 38339023, 2024). "Moreover, endothelial protein C receptor (EPCR) has been identified as an antigenic target for a Vδ2neg γδ TCR expressed by a clonotype heavily expanded after infection with CMV, which is known to infect endothelial tissues." (PMID 30837999, 2019). "ECs are activated by infection and diapedesis and release high amounts of intercellular adhesion molecule (ICAM), P-selectin, and the endothelial protein C receptor (EPCR)." (PMID 35337059, 2022).
cardiovascular disease (5 papers, 2012 to 2024). "Polymorphisms in the PROCR gene were studied in relation to cardiovascular diseases and embolic-thrombotic complications." (PMID 38392646, 2024).
PROCR also shares sentences with these, for which no sentence is quoted: lung carcinoma (6 papers); colitis (5); experimental autoimmune encephalomyelitis (5); anaemia (4); colon carcinoma (4); myocardial infarction (4); rheumatoid arthritis (4); thrombotic disease (4); viral infection (4); diabetes (3); leukemia (3); lung adenocarcinoma (3); triple-negative breast carcinoma (3); antiphospholipid syndrome (2); Arthritis (2); Autoimmunity (2); breast tumor (2); lupus erythematosus (2); lupus nephritis (2); malignant pleural mesothelioma (2); melanoma (2); mesothelioma (2); pneumococcal pneumonia (2); preeclampsia (2); primary sclerosing cholangitis (2); prostate carcinoma (2); psoriasis (2); Thrombocytopenia (2); vascular disorder (2); acute kidney injury (1).
A further 69 diseases each share a sentence with PROCR in 1 paper.